AGGF1 (angiogenic factor with G-patch and FHA domains 1)
Diseases named in the same sentence as AGGF1 in open-access papers (continued):
Sharing a sentence is not in itself a finding about the gene and the disease.
heart failure (1 paper, 2017). Inability of the heart to pump blood at an adequate rate to meet tissue metabolic requirements. "Specifically, we see a reduced AGGF1 level consistently associated with induction of endoplasmic reticulum stress signaling in mouse models and human patients with heart failure." (PMID 28743963, 2017). "AGGF1 protein therapy inhibited heart failure and restored myocardial function (LVEF and LVFS) to nearly normal levels by blocking CHOP-induced apoptosis." (PMID 28743963, 2017). "Immunostaining analysis of heart sections showed that the level of AGGF1 was significantly decreased in patients with heart failure compared with normal controls." (PMID 28743963, 2017). "Moreover, direct injection of AGGF1 protein significantly reduced TAC-induced cardiac apoptosis, hypertrophy, and heart failure, and restored myocardial function in TAC mice to a nearly normal level." (PMID 28743963, 2017). "To test the hypothesis that miR-183-5p is involved in AGGF1-mediated treatment of hypertrophy and heart failure after TAC, we assessed the effect of AGGF1 protein treatment with or without an Antago-miR-183-5p inhibitor in mice after TAC." (PMID 28743963, 2017).
idiopathic pulmonary fibrosis (1 paper, 2023). Idiopathic pulmonary fibrosis (IPF) is a nonneoplastic pulmonary disease that is characterized by the formation of scar tissue within the lungs in the absence of any known cause. "Pirfenidone, a treatment agent for idiopathic pulmonary fibrosis, inhibits TAA-associated vascular inflammation and remodeling in wild type mice, but not in Aggf1+/- mice." (PMID 37081014, 2023).
ischemia (1 paper, 2022). A hypoperfusion of the BLOOD through an organ or tissue caused by a PATHOLOGIC CONSTRICTION or obstruction of its BLOOD VESSELS, or an absence of BLOOD CIRCULATION. "To verify whether Gsα regulated ischemic angiogenesis via AGGF1 in vivo, we administrated adenovirus expressing LacZ or AGGF1 to CTR and Gsα ECKO mice via tail vein injection, then ligated the left femoral artery to induce hindlimb ischemia in these mice." (PMID 35958407, 2022).
Klippel-Trenaunay syndrome (1 paper, 2017). "AGGF1 plays a role in angiogenesis and altered expression of AGGF1 is associated with vascular malformations consistent with Klippel-Trenaunay syndrome (KTS)." (PMID 29340079, 2017).
limb ischemia (1 paper, 2012). A ischemia that involves the limb. "Our data indicate that AGGF1 can serve as a novel therapeutic agent for the treatment of critical limb ischemia as increased AGGF1 expression in skeletal muscles enhanced limb function, increased blood flow, and healed ischemic ulcers in a mouse hindlimb ischemia model." (PMID 23110058, 2012).
liver cancer (1 paper, 2025). An epithelial or non-epithelial malignant neoplasm that arises from the liver. "Notably, AGGF1 can promote angiogenesis of liver cancer, is overexpressed in liver cancer, and predicts poor prognosis." (PMID 41578779, 2025).
Myocardial fibrosis (1 paper, 2017). "Aggf1+/− mice showed an enhanced level of myocardial fibrosis induced by TAC." (PMID 28743963, 2017).
non-small cell lung carcinoma (1 paper, 2025). A group of at least three distinct histological types of lung cancer, including non-small cell squamous cell carcinoma, adenocarcinoma, and large cell carcinoma. "In the study «The Relationship Between UBE2C and AGGF1 Overexpression and Tumor Angiogenesis in Non-Small Cell Lung Cancer» there were 154 patients." (PMID 40786517, 2025).
peripheral artery disease (1 paper, 2022). "However, we found that integrin α5β1 acted as a receptor for AGGF1 in endothelial cells, activated FAK-Src-AKT signaling, and modulated the signaling and functions of AGGF1 in endothelial cells and therapeutic angiogenesis in a model for peripheral artery disease (PAD)." (PMID 35202649, 2022).
thoracic aortic aneurysm (1 paper, 2023). An aneurysm formed in the wall of the proximal portion of the descending aorta proceeding from the arch of the aorta. "This raises the hope that pirfenidone may be used to treat pressure-overload-induced vasculopathies such as thoracic aortic aneurysms and dissection in combination with AGGF1." (PMID 37081014, 2023).
urothelial carcinoma (1 paper, 2017). A malignant neoplasm derived from the transitional epithelium of the urinary tract (urinary bladder, ureter, urethra, or renal pelvis). "The probable reason was that hypoxic condition was common in the high-grade urothelial carcinoma and the down-regulating of the AGGF1 protein had an apparent protective role." (PMID 29340079, 2017). "However, in high-grade urothelial carcinoma, the AGGF1 expression was significantly lower than that in low-grade urothelial carcinoma or in normal control." (PMID 29340079, 2017). "However, the proportion of strong AGGF1 expression was significantly lower in the high-grade urothelial carcinoma group than that in the normal urothelium tissue group." (PMID 29340079, 2017).
vascular tumors (1 paper, 2021). "AGGF1 has also been detected in vascular tumors, so further evaluation of its role in MVP of AVM will be of interest." (PMID 34541367, 2021).
tumor (12 papers, 2009 to 2025). "In HCC patients, the increased AGGF1 expression is also associated with tumor angiogenesis (microvessel density, MVD)." (PMID 29340079, 2017). "This study examined the potential clinical significance of taurolactone, a novel drug renowned for its anti-tumor and anti-angiogenesis properties, particularly concerning angiogenic factor AGGF1 and angiogenesis mimicry in individuals diagnosed with HCC." (PMID 38773427, 2024). "VEGF and AGGF1 serve as key regulators of tumor angiogenesis, playing a critical role in tumor growth." (PMID 38773427, 2024). "AGGF1 has been identified as a factor essential for both physical angiogenesis and pathological tumor angiogenesis in vivo." (PMID 35958407, 2022). "Recent studies have found that AGGF1 is expressed in some types of malignant tumors and is closely related to tumor angiogenesis." (PMID 30858758, 2019). "These in vivo and vitro data suggest that the elevated expression of AGGF1 is likely correlated with tumor invasion." (PMID 31881864, 2019). "Both subcutaneous xenograft groups using transfected cells with sh-AGGF1 had dramatically decreased abilities to form tumors compared to those in control groups, as indicated by the final xenograft tumor size." (PMID 30858758, 2019). "Of note, all the patients with multiple tumors belong to positive AGGF1 expression and the positive AGGF1 expression was significantly correlated with tumor number (P=0.035, chi-square test)." (PMID 29340079, 2017). "In tumor tissues, most cases were positive for AGGF1 expression, with a positive rate of 63.3% (50/79), while in peritumor tissues, the positive rate was much lower (37.5%, 9/24)." (PMID 29340079, 2017). "Expression of AGGF1 in tumor tissue is relatively different to detect, however, the study of the serum AGGF1 level has not been reported up to now." (PMID 29340079, 2017). "According to these data above, our evidence indicated that aberrant expression of AGGF1 in HCC tumor tissue was correlated with MVD." (PMID 29340079, 2017). "Reduced levels of VEGF and AGGF1 may result in a reduction in the number of blood vessels within tumors, consequently limiting the delivery of oxygen and nutrients to tumor cells." (PMID 38773427, 2024). "Many nuclear proteins containing FHA domains, like AGGF1, CHK2, and MDC1, transcriptionally regulate the expression of genes associated with cell cycle checkpoints, DNA repair, and apoptosis to achieve their tumor suppression function." (PMID 37452081, 2023). "Besides, AGGF1 knockdown group had smaller tumor xenografts than those in the control group in vivo." (PMID 30858758, 2019). "However, despite the angiogenic activity of AGGF1 in several disease models, its role in the tumor is still limited and controversial." (PMID 29340079, 2017). "Our present results suggest that AGGF1 may contribute to tumor angiogenesis of HCC and could be a new potential therapeutic target for anti-angiogenesis treatment of HCC." (PMID 29340079, 2017). "One gene was overexpressed in tumour, the AGGF1, a recently discovered potent angiogenic." (PMID 19662092, 2009). "Knockdown of AGGF1 dramatically inhibited the invasion and migration of MKN-45 and MGC-803 cells (all P < 0.01) in vitro, and suppressed the tumor growth of nude mice xenograft model in vivo." (PMID 30858758, 2019). "Aberrant upregulated expression of AGGF1 was highly correlated with tumor invasion (p < 0.001), LNM (p < 0.001), distant metastasis (p = 0.012), advanced AJCC stage (p < 0.001), and tumor recurrence (p = 0.004)." (PMID 31881864, 2019). "The expression levels of AGGF1, vascular endothelial growth factor (VEGF) and microvessel density (MVD) were identified by immunohistochemistry in 79 HCC tumor tissues and 24 corresponding peritumor tissues." (PMID 29340079, 2017).
tumor (continued). "It was found that miR-27a functioned as a tumor promoter in various cancers through targeting MAP2K4, AGGF1, prohibitin, and other genes that regulate specificity protein transcription factors and the G2-M checkpoint." (PMID 25329674, 2014). "In the multivariate analysis, after adjusting for UBE2C, AGGF1, microvessel density (MVD), tumor size, LNM, and TNM stage, positive VM status remained an independent predictor of mortality, increasing the risk by 2.1-fold (multivariate HR 2.107, 95% CI: 1.226–3.622, p=0.007)." (PMID 40786517, 2025). "contribute to tumor angiogenesis in HCC, which indicates that AGGF1 may be a new potential therapeutic target for anti-angiogenesis treatment for patients with HCC." (PMID 29340079, 2017). "In the present study, the expression of AGGF1, vascular endothelial growth factor (VEGF), and CD34-labeled microvessel density (MVD) in HCC tumor tissues and peritumoral tissues were investigated by immunohistochemistry and evaluated the relationship between the clinical outcome." (PMID 29340079, 2017).
cancer (4 papers, 2014 to 2023). A tumor composed of atypical neoplastic, often pleomorphic cells that invade other tissues. "Presently, cancer angiogenesis research is mainly focused on VEGF, but some studies have identified that circRNA can regulate cancer angiogenesis via AGGF1, ZIC4, and SOX13." (PMID 37616050, 2023). "A series of studies have also reported that the expression level of AGGF1 in cancer tissues was clearly higher than in adjacent normal tissues, predicting poor prognosis." (PMID 31881864, 2019). "AGGF1 ubiquitously expresses in human normal cells as well as cancer cells." (PMID 31881864, 2019). "This is remarkable not only because RAF1 fusions have never been identified in this cancer type before, but also because all seven examples involved a novel partner gene, AGGF1 (angiogenic factor with G patch and FHA domains 1)." (PMID 25204415, 2014).
nervous system diseases (2 papers, 2018 to 2022). "Recently, angiogenic factor with G-patch and FHA domain 1 (Aggf1) was shown to inhibit inflammatory effect and preserve vascular integrity in non-nervous system diseases." (PMID 29885663, 2018).
cardiovascular diseases (1 paper, 2017). "As ER stress is an evolutionarily conserved process involved in numerous diseases, AGGF1 protein therapy may serve as a new treatment not only for cardiovascular diseases, but also for many other diseases associated with ER stress." (PMID 28743963, 2017). "Thus, AGGF1 protein therapy that regulates ER stress signaling may also be a promising strategy to clinically intervene with these non-cardiovascular diseases." (PMID 28743963, 2017).
vasculopathies (1 paper, 2023). "We recommend combined pirfenidone/AGGF1 treatment as a strategy for management of IPF and other vasculopathies associated with vascular inflammation and remodeling." (PMID 37081014, 2023).
AGGF1 also shares sentences with these, for which no sentence is quoted: colon cancer (2 papers); mesothelioma (2); subarachnoid hemorrhage (2); Heart Disease (1); Hypertension (1); hypertrophy (1); infection (1); ischemic stroke (1); liver cirrhosis (1); liver disease (1); Marfan syndrome (1); metabolic dysfunction-associated steatohepatitis (1); Nephropathy (1); ovarian carcinoma (1); Stroke (1); vascular malformation (1).